SLC25A30 (solute carrier family 25 member 30)
Description:
Antiporter that transports inorganic anions (sulfate, sulfite, thiosulfate and phosphate) and, to a lesser extent, a variety of dicarboxylates (e.g. malonate, malate and citramalate) and, even more so, aspartate. The sulfate/sulfate exchange is much higher than the phosphate/phosphate and malate/malate exchanges. The transport affinities is higher for sulfate and thiosulfate than for any other substrate. May catalyze the export of sulfite and thiosulfate (the hydrogen sulfide degradation products) from the mitochondria, thereby modulating the level of the hydrogen sulfide (Probable). Also may mediate a very low unidirectional transport of sulfate, phosphate and (S)-malate.
Synonyms: KMCP1
Tractability: Antibody: UniProt predicts a signal peptide or a membrane-spanning region. PROTAC: ubiquitination databases record sites on it; its protein half-life has been measured.
Gene: Protein-coding gene on chromosome 13 (45,393,316 to 45,418,455, reverse strand). Ensembl gene ENSG00000174032.
Subcellular location: Mitochondrion inner membrane
Subcellular location (Human Protein Atlas): Nucleoplasm
Gene Ontology:
Molecular function: protein binding; solute:inorganic anion antiporter activity
Biological process: inorganic anion transport; transmembrane transport
Cellular component: mitochondrion; mitochondrial inner membrane
Genetic constraint (gnomAD): Loss-of-function variants: 23 observed, 30.23 expected, observed/expected ratio (o/e) 0.76, 90% interval 0.55 to 1.08. The upper end of that interval is the gene's LOEUF score, 1.08, which puts it in group 4 of 6, group 1 being the genes least tolerant of losing a copy. Missense variants: 233 observed, 306.86 expected, observed/expected ratio (o/e) 0.76, 90% interval 0.68 to 0.85. Synonymous variants: 103 observed, 115.41 expected, observed/expected ratio (o/e) 0.89, 90% interval 0.76 to 1.05.
Homologues: Orthologues: chimpanzee SLC25A30 (99% identical), dog SLC25A30 (97% identical), macaque SLC25A30 (96% identical), pig SLC25A30 (95% identical), guinea pig SLC25A30 (94% identical), rat Slc25a30 (93% identical), mouse Slc25a30 (92% identical), tropical clawed frog slc25a30 (89% identical), rabbit SLC25A30 (76% identical). Paralogues in human: SLC25A14 (80% identical), SLC25A27 (41% identical), UCP2 (38% identical), UCP3 (38% identical), UCP1 (35% identical), SLC25A35 (30% identical), SLC25A13 (27% identical), SLC25A12 (27% identical), SLC25A10 (27% identical), SLC25A22 (27% identical), SLC25A38 (26% identical), SLC25A39 (26% identical), and 37 more.
Diseases named in the same sentence as SLC25A30 in open-access papers:
SLC25A30 is named in the same sentence as 4 diseases in open-access papers, as found by Europe PMC text mining. Sharing a sentence is not in itself a finding about the gene and the disease. The quoted sentences say what the papers report.
cancer (2 papers, 2024). A tumor composed of atypical neoplastic, often pleomorphic cells that invade other tissues. "Both SLC25A30 and PTBP2 are described to influence mitochondrial function and promote cancer cell proliferation." (PMID 38604503, 2024).
SLC25A30 also shares sentences with these, for which no sentence is quoted: autism (1 paper); infection (1); neurodevelopmental disorder (1).